AFP (alpha fetoprotein)
Diseases named in the same sentence as AFP in open-access papers (continued):
Sharing a sentence is not in itself a finding about the gene and the disease.
pancreatic cancer (49 papers, 2010 to 2025). "Research has shown that AFP-producing pancreatic cancer cells possess self-renewal and differentiation capabilities, and their enhanced tumorigenic potential has been demonstrated through xenotransplantation experiments." (PMID 40430002, 2025). "AFP-producing pancreatic cancer exhibits unique clinical characteristics, including high malignancy and early metastatic potential, leading to a poor prognosis." (PMID 40430002, 2025). "Pancreatic HC should be considered when encountering a bulky tumor of the pancreas with elevated serum AFP levels, and further case series and analysis are needed to determine the appropriate treatment strategy." (PMID 40612981, 2025). "In relation to pancreatic cancers, AFP-producing pancreatic cancer is usually derived from acinar cells; AFP-producing adenocarcinoma from ductal cells is relatively rare." (PMID 38817451, 2024). "The levels of eight serum tumor markers (CA19-9, CEA, CA242, CA72-4, CA50, CA125, CA153, and AFP) commonly used in gastroenterological cancer were analyzed in all stages of pancreatic cancer." (PMID 26745601, 2016). "We compared the serum levels of CA19-9, CA125, FER, CA242, CEA, CA15-3, β-HCG, AFP, NSE, PSA, f-PSA and HGH associated with pancreatic cancer, and found that simultaneous analysis of them was important for the diagnosis of pancreatic cancer." (PMID 25381564, 2014). "McIntire found elevated AFP levels in 24% of patients with pancreatic cancer, and even lower sensitivity has been noted in other series." (PMID 24281109, 2010). "Therefore, while AFP production is a marker of aggressive disease, further investigation into its role and the associated resistance mechanisms may identify novel therapeutic targets to improve treatment responses in patients with AFP-producing pancreatic cancer." (PMID 40430002, 2025). "Serum AFP levels were elevated in all pediatric cases of ACCs in which it was measured and it has been hypothesized that AFP production in pancreatic neoplasms is related to acinar differentiation." (PMID 26137463, 2015). "However, AFP has seemingly a role in detection of rare tumors of the pancreas like acinar cell tumor and pancreatoblastoma." (PMID 24281109, 2010). "Indeed, the increase in core-fucosylated alpha-fetoprotein (AFP) in the serum of HCC patients can indicate cancer progression more specifically than the increase in total AFP; in addition, the role of core-fucosylated haptoglobin has been described in the diagnosis of pancreatic cancer." (PMID 36980181, 2023). "Similar to pancreatic cancer, in which a higher preoperative CA 19-9 was associated with surgical-related muscle loss, we have discovered that a more advanced HCC in terms of AFP or tumor size could also result in more pronounced muscle loss after surgery." (PMID 36464698, 2022). "However, AFP appears to be of limited value in the diagnosis of pancreatic cancer." (PMID 24281109, 2010). "For example, alpha-fetoprotein (AFP) is a widely accepted biomarker for the detection of HCC, while CA-199 is sensitive to pancreatic cancer, and carcinoembryonic antigen (CEA) is commonly used for colon cancer patients." (PMID 37546394, 2023). "More importantly, TAP was detected more frequently among patients with cancer than other known markers, including AFP and CA19-9, in liver and pancreatic cancer, suggesting the promise of TAP as universal cancer marker." (PMID 32176062, 2020). "Increased levels of fucosylation have been reported in cancer, such as increased core-fucosylation of AFP in HCC, and increased fucosylation of haptoglobin in ovarian, lung, breast and pancreatic cancer." (PMID 20704698, 2010). "The study demonstrates that IORT-DT is an effective treatment for liver and pancreatic tumours LPT, significantly reducing AFP and CA19-9 levels, improving liver and kidney function, lowering recurrence rates, and enhancing survival outcomes compared to conventional treatments." (PMID 40951893, 2025).
pancreatic cancer (continued). "Initially, we reviewed the clinical data of patients, conducted univariate analysis, and combined with literature research on prognostic factors of pancreatic cancer, finally including 11 biological indicators (IL-2, IL-4, IL-6, IL-17, IFN-γ, NLR, LDH, CEA, AFP, CA19-9, β2-MG)." (PMID 41384105, 2025). "Additionally, biomarkers such as AFP, CD44, Galectin-3, and CEA exhibit notable importance, reinforcing their relevance in pancreatic cancer detection." (PMID 40217526, 2025). "Moreover, TAP-positive incidence was found to be more frequent than AFP and CA19-9 in liver and pancreatic cancer, respectively, suggesting the advantage of TAP over these established markers." (PMID 32176062, 2020). "Some tumor markers (CA19-9, ACE y AFP) were negative, but ultrasound exams and tomography revealed a tumor that was strongly suggestive of pancreatic cancer." (PMID 28789670, 2017). "All pancreatic cancer tissues were shown to contain no expression of AFP protein." (PMID 35783291, 2022). "Additionally, we emphasize the importance of AFP as a therapeutic target by specifically discussing its effects on tumor progression, metastasis, immune evasion, and treatment resistance across various cancers, including HCC and testicular, ovarian, gastric, colorectal, and pancreatic cancers." (PMID 40430002, 2025).
testicular cancer (47 papers, 1998 to 2026). A primary or metastatic malignant neoplasm that affects the testis. "Testicular cancer, although more common among younger men, also suffers from diagnostic challenges: traditional serum markers such as AFP, hCG, and LDH are inadequate for early diagnosis in a substantial proportion of patients." (PMID 40391154, 2025). "systematically reviewed the data for the diagnostic accuracy of serum β-hCG, LDH, and AFP in monitoring testicular cancer recurrence in adults." (PMID 37781207, 2023). "For testicular cancer, AFP (alpha-fetoprotein), β-hCG (beta-human chorionic gonadotropin), and LDH (lactate dehydrogenase) are essential for staging and treatment planning." (PMID 41563267, 2026). "He had normal laboratory values, including normal tumor markers for testicular cancer, alpha‐fetoprotein (AFP), human chorionic gonadotropin (hCG), and lactate dehydrogenase (LDH)." (PMID 41185737, 2025). "Among patients with testicular cancer, 26 (61.9%) exhibited abnormal levels of at least one of the classical serum tumor markers (AFP, β-hCG, LDH)." (PMID 41283275, 2025). "Actually the diagnosis of testicular cancer is based on clinical examination, imaging techniques, and serum markers like alpha-fetoprotein (AFP), human chorionic gonadotropin (hCG), and lactate dehydrogenase (LDH)." (PMID 40391154, 2025). "Nevertheless, elevated AFP concentrations have also been documented in various other conditions, including cerebellar ataxia and testicular cancer." (PMID 38494878, 2024). "Nicholson considered that the recommendation of β-hCG, LDH, and AFP for monitoring testicular cancer recurrence during follow-up in international guidelines is lacking in supporting evidence." (PMID 37781207, 2023). "With the progress of medical technology and the popularization of related detection technologies, such as ultrasound, CT, and AFP, testicular cancer can be found and treated earlier, and both missed diagnosis and misdiagnosis rates can be reduced." (PMID 36148350, 2022). "Two of these patients (Patients 2 and 5) achieved a complete response as assessed by testicular cancer tumor markers AFP or hCG and were still in remission after completing the six cycles." (PMID 33135391, 2021). "The presence of polymorph nuclear cells within the intertubular tissue was reflected by an increase in testicular α-fetoprotein (AFP) which is a 70 kilo Dalton single-chain glycoprotein predicts the development of testicular cancer." (PMID 33507682, 2021). "AFP is physiologically synthesized in the liver and can be detected at increased levels in testicular cancer patients as well as under other benign liver diseases, which have been reported as a misleading cause of interpretation of TGCTs clinical course." (PMID 31906360, 2020). "Both white blood cell counts and NLR can be used as a simple test in the diagnosis of testicular cancer besides the well-known accurate serum tumor markers as AFP (alpha fetoprotein), hCG (human chorionic gonadotropin) and LDH (lactate dehydrogenase)." (PMID 27136467, 2016). "Among them, 3 genes were approved by FDA for cancer diagnosis, including: EGFR, KLK3 (PSA) and AFP for the diagnosis of colon, prostate and testis cancers, respectively." (PMID 22761861, 2012). "However, owing to limitations in the sensitivity and specificity of AFP, it cannot replace tissue diagnosis in the management of testicular cancer." (PMID 40430002, 2025). "The early detection of testicular cancer although remains an important clinical challenge.In fact traditional tumor markers such as AFP, hCG, and LDH are useful for monitoring the progression of testicular cancer but it's not always possbile to use them for early diagnosis." (PMID 40391154, 2025). "Additionally, AFP levels can assist in staging testicular cancer, with higher levels often correlating with more advanced disease, thereby influencing treatment planning and surgical approaches." (PMID 40430002, 2025).
testicular cancer (continued). "Consequently, further research, potentially involving the integration of other biomarkers, is needed to more accurately assess the impact of elevated serum AFP levels on cancer progression, recurrence potential, and the need for additional therapies in testicular cancer." (PMID 40430002, 2025). "From the 1970s, serum tumor markers, such as beta human chorionic gonadotropin (bHCG), alpha fetoprotein (AFP), and lactate dehydrogenase (LDH), have been implemented in the routine clinical management of testicular cancer (TC)." (PMID 36983756, 2023). "Alpha-fetoprotein (AFP), human chorionic gonadotropin (HCG) and lactate dehydrogenase (LDH) are used as serum markers of testicular cancers." (PMID 31450698, 2019). "Testicular cancer is staged using the AJCC TNM system and based on the beta-hCG, LDH, and AFP levels (The National Comprehensive Cancer Network [NCCN], 2018d)." (PMID 30250431, 2018). "This case underscores the complexity of testicular cancer presentation and management, especially in the context of a high AFP and HCG levels without evidence of metastatic disease." (PMID 39697937, 2024). "While the serum tumor markers alpha fetoprotein (AFP), beta-human chorionic gonadotropin (β-hCG), and lactate dehydrogenase (LDH) are widely utilized in testicular cancer, miRNAs are under investigation as promising markers for diagnosis, prognosis, therapeutic monitoring, and surveillance." (PMID 39273446, 2024). "In a study of nearly 1500 testicular cancer patients, more than 60% of patients with non-seminoma testicular cancer manifested elevated AFP levels, making it the most commonly increased tumor marker in testicular cancer." (PMID 37627177, 2023). "CtDNA detection of testicular cancer remained high, with an 84% sensitivity and 97% specificity for patients without established testicular cancer biomarkers, including alpha-fetoprotein, human chorionic gonadotropin, placental alkaline phosphatase, and lactate dehydrogenase." (PMID 38927984, 2024). "Although, guidelines recommend the use of all three tumor markers AFP, ß-HCG and LDH, they should be used with caution due to their partly non-specificity for testicular cancer." (PMID 34854948, 2022). "A recent review made the following conclusion: “Having systematically reviewed the available literature, we found surprisingly little evidence to guide optimal testing with biomarkers (AFP, hCG and LDH) routinely used during follow-up for testicular cancer recurrence”." (PMID 31652641, 2019). "It has been recognized that the tumour markers alpha-fetoprotein (AFP) and human chorionic gonadotrophin (HCG) may show a transient elevation after the initiation of chemotherapy in non-seminomatous testicular cancer." (PMID 9823978, 1998).
chronic hepatitis C (40 papers, 2008 to 2026). "DCR was associated with AFP > 400 ng/ml (OR 0.57, 95% CI 0.36–0.9), European sites (OR 3.97, 95% CI 1.91–8.24), and chronic hepatitis C (OR 2.04, 95% CI 1.14–3.66) in univariable analysis." (PMID 33995594, 2021). "Since this is the era of direct-acting drug therapy for chronic hepatitis C, further studies are warranted to define the role of AFP in patients with HCV-associated HCC and direct-acting drug treatment." (PMID 27304617, 2016). "In this study, we attempted to identify a specific gene expression signature by performing microarray analysis on the livers of patients with chronic hepatitis C and AFP elevation, which is considered high risk for development of HCC." (PMID 22681639, 2012). "The aim was to analyse the hepatic gene expression signature in chronic hepatitis C patients with elevated AFP, who were at high risk for HCC." (PMID 22681639, 2012). "In a previous study, we have demonstrated that AFP was negatively associated with treatment response in 100 patients with chronic hepatitis C in Egypt." (PMID 18545682, 2008). "The prevalence of abnormally elevated AFP levels in patients with chronic hepatitis C is about 10% to 43% in Western countries." (PMID 33490235, 2020). "Among patients in the two groups, male gender, single tumor >2 cm, BCLC stage 0 or A, AFP < 20ng/dL, chronic hepatitis C or B, and Child-Pugh class A were predominant." (PMID 28068369, 2017). "A few studies have shown that phlebotomy can reduce serum AFP levels in patients with chronic hepatitis C." (PMID 27335844, 2014). "Liver tissue samples from 48 chronic hepatitis C patients were stratified by their serum AFP levels and analysed for gene expression profiles." (PMID 22681639, 2012). "We have reported the effect of IFN on alpha-fetoprotein (AFP) changes in 40 patients with chronic hepatitis C." (PMID 23173649, 2012). "AKR1B10 was up-regulated in association with serum AFP, and was an independent risk factor for HCC in chronic hepatitis C patients, suggesting its possible involvement at a very early stage of hepatocarcinogenesis." (PMID 22681639, 2012). "Serial AFP measurements in patients with chronic hepatitis C are useful for identifying persons with advanced fibrosis and help to determine which patients need periodic liver ultrasound screening to detect HCC." (PMID 22690233, 2012). "We examined the association between serum alpha-fetoprotein (AFP) level and sustained virological response (SVR) in 93 chronic hepatitis C patients." (PMID 18545682, 2008). "Serum AFP should be added to the list of factors predictive of treatment response in chronic hepatitis C." (PMID 18545682, 2008). "Serum AFP level is an important factor in predicting HCC development after the antiviral therapy for Japanese patients with chronic hepatitis C, the mechanism of which might involve its significant associations with the SNP genotype of PNPLA3." (PMID 23772356, 2013). "In conclusion, serum AFP level is an important factor in predicting HCC development after the antiviral therapy for Japanese patients with chronic hepatitis C, the mechanism of which might involve its significant associations with the SNP genotype of PNPLA3." (PMID 23772356, 2013). "In this study, to precisely investigate the molecular alteration in the very early stages of hepatocarcinogenesis, we used a cDNA microarray-based strategy to compare the gene expression profiles of chronic hepatitis C patients who were stratified according to their AFP levels." (PMID 22681639, 2012). "(2013) for chronic hepatitis C patients included variables such as hyaluronic acid, TGF-β1, α2-macroglobulin, Matrix Metalloproteinase (MMP)-2, apolipoprotein-A1, urea, MMP-1, alpha-fetoprotein, haptoglobin, red blood cell count, hemoglobin, and TIMP-1." (PMID 41551471, 2026). "Patient 3, a 67-year-old male with chronic hepatitis C, presented with an HCC-like lesion and elevated AFP." (PMID 40843884, 2025).
chronic hepatitis C (continued). "Iron reduction by therapeutic phlebotomy can reduce serum AFP and GGT levels in chronic hepatitis C patients." (PMID 27335844, 2014). "Thus, in patients with chronic Hepatitis C, a reactive expression of the AFP gene, as shown in hepatic necroinflammation and hepatocellular proliferation, may be associated with a decrease in albumin gene transcription and may lead to a lower serum albumin level." (PMID 22675639, 2012). "One by one, the following not significant variables were removed: chronic hepatitis C (p = 0.96), length within the waiting list (p = 0.58), alpha-fetoprotein (p = 0.21) and HCC status (p = 0.90)." (PMID 28403219, 2017). "Previous analyses of the HALT-C trial and other populations showed that serum AFP is elevated in patients with advanced chronic hepatitis C, with or without HCC, especially among female and African American patients." (PMID 27688741, 2016). "In conclusion, this study confirms the value of serum AFP levels in predicting treatment outcome in patients with chronic hepatitis C, regardless of the infecting genotype." (PMID 18545682, 2008). "Based on the results, the combination of col-III/MMP-1 ratio (CMR), alpha-fetoprotein (AFP), aspartate aminotransferase (AST)/alanine aminotransferase (ALT) ratio and platelet count has been suggested for F2–F4 staging of fibrosis in patients with chronic hepatitis C infection." (PMID 32414178, 2020). "Moreover, serum AFP levels may elevate in chronic hepatitis C virus infection without evidence of HCC." (PMID 27997559, 2016). "Another Asian cohort, including 654 patients with chronic hepatitis C with no documentation of HCC and no history of liver decompensation, concluded that increased AFP levels paralleled with age, necroinflammation score, high transaminase levels and low platelet count." (PMID 32341704, 2020).